TINF2 (TERF1 interacting nuclear factor 2)
Description:
Component of the shelterin complex (telosome) that is involved in the regulation of telomere length and protection. Shelterin associates with arrays of double-stranded TTAGGG repeats added by telomerase and protects chromosome ends; without its protective activity, telomeres are no longer hidden from the DNA damage surveillance and chromosome ends are inappropriately processed by DNA repair pathways. Plays a role in shelterin complex assembly. Isoform 1 may have additional role in tethering telomeres to the nuclear matrix.
Synonyms: TIN2; DKCA3; DKCA5
Tractability: PROTAC: UniProt records ubiquitination sites on it; ubiquitination databases record sites on it.
Gene: Protein-coding gene on chromosome 14 (24,238,286 to 24,242,663, reverse strand). Ensembl gene ENSG00000092330.
Subcellular location: Nucleus; Chromosome, telomere; Nucleus matrix (Isoform 1)
Subcellular location (Human Protein Atlas): Nuclear bodies
Pathways (Reactome):
Cell Cycle: Inhibition of DNA recombination at telomere; Packaging Of Telomere Ends; Polymerase switching on the C-strand of the telomere; Processive synthesis on the C-strand of the telomere; Removal of the Flap Intermediate from the C-strand; Telomere C-strand (Lagging Strand) Synthesis; Telomere C-strand synthesis initiation; Telomere Extension By Telomerase
DNA Repair: Cleavage of the damaged purine; Cleavage of the damaged pyrimidine; Recognition and association of DNA glycosylase with site containing an affected purine; Recognition and association of DNA glycosylase with site containing an affected pyrimidine
Cellular responses to stimuli: DNA Damage/Telomere Stress Induced Senescence
Reproduction: Meiotic synapsis
Gene Ontology:
Molecular function: DNA binding; protein binding; telomeric DNA binding
Biological process: negative regulation of epithelial cell proliferation; negative regulation of telomere maintenance via telomerase; protein localization to chromosome, telomeric region; regulation of telomere maintenance via telomere lengthening; telomere assembly; telomere capping; positive regulation of telomere maintenance
Cellular component: chromosome, telomeric region; nuclear body; nuclear telomere cap complex; perinucleolar chromocenter; shelterin complex; nucleoplasm; nuclear matrix; nucleus
Genetic constraint (gnomAD): Loss-of-function variants: 27 observed, 54.11 expected, observed/expected ratio (o/e) 0.5, 90% interval 0.37 to 0.69. The upper end of that interval is the gene's LOEUF score, 0.69, which puts it in group 2 of 6, group 1 being the genes least tolerant of losing a copy. Missense variants: 496 observed, 587.32 expected, observed/expected ratio (o/e) 0.84, 90% interval 0.78 to 0.91. Synonymous variants: 223 observed, 229.5 expected, observed/expected ratio (o/e) 0.97, 90% interval 0.87 to 1.09.
Gene-disease validity (ClinGen):
ClinGen rates the evidence that TINF2 causes each of these diseases.
dyskeratosis congenita, autosomal dominant 3 (autosomal dominant): Definitive.
Homologues: Orthologues: chimpanzee TINF2 (99% identical), macaque TINF2 (90% identical), pig TINF2 (82% identical), dog TINF2 (79% identical), rabbit TINF2 (62% identical), rat Tinf2 (60% identical), mouse Tinf2 (58% identical), tropical clawed frog tinf2 (22% identical), zebrafish tinf2 (19% identical), zebrafish zgc:113263 (17% identical).
Diseases named in the same sentence as TINF2 in open-access papers:
TINF2 is named in the same sentence as 77 diseases in open-access papers, as found by Europe PMC text mining. Sharing a sentence is not in itself a finding about the gene and the disease. The quoted sentences say what the papers report.
dyskeratosis congenita (27 papers, 2009 to 2026). Dyskeratosis congenita (DC) is a rare ectodermal dysplasia that often presents with the classic triad of nail dysplasia, skin pigmentary changes, and oral leukoplakia associated with a high risk of bone marrow failure (BMF) and cancer. "Case Presentation: A female patient diagnosed with dyskeratosis congenita due to a heterozygous TINF2 mutation was followed from early childhood." (PMID 42122061, 2026). "Mutations in TINF2, the gene encoding TIN2, have been linked to telomere-related disorders such as dyskeratosis congenita, Revesz syndrome, and Hoyeraal–Hreidarsson syndrome." (PMID 40141057, 2025). "TINF2 is mutated in patients with dyskeratosis congenita, which is a heterogeneous inherited bone marrow failure syndrome." (PMID 38382674, 2024). "Pathogenic missense and truncating TINF2 mutations are causative for dyskeratosis congenita (DC), a rare, dominantly inherited bone marrow failure syndrome characterized by mucocutaneous abnormalities and cancer predisposition." (PMID 35590014, 2023). "TBDs caused by TINF2 mutations clinically present with a spectrum of phenotypes, from silent carriers to a set of overlapping conditions, such as dyskeratosis congenita (DC), Hoyeraal-Hreidarsson syndrome, Revesz syndrome." (PMID 35873475, 2022). "The gene mutations in all cases were consistent with those of dyskeratosis congenita, including TINF2 mutations in three cases and DKC1 mutations in one case." (PMID 33734615, 2021). "Severe deleterious mutations in TINF2 have also been identified in patients with dyskeratosis congenita that is characterized by very short telomeres." (PMID 31171785, 2019). "TINF2, the gene that encodes TIN2, is the second most commonly mutated gene in the telomere biology disorder dyskeratosis congenita (DC)." (PMID 29581185, 2018). "TINF2 is a known, disease-causing gene of AD Revesz syndrome and dyskeratosis congenita." (PMID 30477545, 2018). "Patients with a clinical diagnosis of dyskeratosis congenita (DKC), particularly those with TINF2 mutation associated DKC, should undergo routine CT and MRI examinations of the central nervous system (CNS)." (PMID 33734615, 2021). "Mutations in TINF2, which encodes TIN2, that are found in dyskeratosis congenita (DC) result in very short telomeres and cluster in a region shared by the two TIN2 isoforms, TIN2S (short) and TIN2L (long)." (PMID 29581185, 2018). "Mutations of DKC1 which encodes dyskerin, TRF1-interacting nuclear factor (TINF2) encoding shelterin component TIN2, genes encoding TERT and TER accounts for most of the dyskeratosis congenita cases." (PMID 29364142, 2018). "Telomeropathies include dyskeratosis congenita (DKC), in which a disease-causing variant is often found within the dyskerin (DKC1) gene on the X chromosome or other telomere maintenance genes such as TINF2, TERC, TERT, CTC1, and other genes." (PMID 40440483, 2025). "Individuals with dyskeratosis congenita (DC), a cancer susceptibility and inherited bone marrow failure syndrome (IBMFS), have mutations in genes important in telomere biology, including DKC1, TERC, TERT, TINF2, NHP2 and NOP10." (PMID 21113082, 2010).
melanoma (6 papers, 2020 to 2024). A malignant, usually aggressive tumor composed of atypical, neoplastic melanocytes. "Recently, a truncating germline TINF2 mutation, p.Trp198fs, was reported in a large family with several papillary thyroid carcinoma and melanoma cases, and it showed complete disease co-segregation." (PMID 35590014, 2023). "All four TINF2 p.Tyr312Ter carriers from the unselected cohort had family history of cancer, but only one of the families showed cancer types (one melanoma case) previously linked to TINF2-related cancer susceptibility." (PMID 35590014, 2023). "Similarly, a recent report identified a TINF2 truncation mutation in a large family affected by thyroid cancer and melanoma." (PMID 33258446, 2020). "TINF2 mutation was described in a family with melanoma and thyroid cancer predisposition." (PMID 33218058, 2020). "We also detected another shelterin gene truncating mutation affecting the TINF2 gene that we included in the low-risk gene category; however, another TINF2 truncation has recently been described to segregate with multiple thyroid cancer and melanoma in one family." (PMID 33050356, 2020). "A frameshift mutation in the TINF2 gene (TINF2 p.Trp198fs) was identified, showing complete co-segregation with PTC and melanoma in the key family." (PMID 38571492, 2024). "The spectrum of cancers in the TINF2 families studied here is broad, including breast cancer, colorectal cancer, thyroid cancer, and melanoma, and several patients had multiple independent malignancies." (PMID 33258446, 2020). "The authors further correlated the presence of TINF2 (a shelterin gene) to families with PTC and melanoma." (PMID 33218058, 2020).
aplastic anaemia (5 papers, 2011 to 2024). "Among the 224 consecutive patients with different forms of bone marrow failure (46 with DC, 122 with aplastic anaemia and 57 with some features of DC), we have identified 16 new families with variants in exon 6 of the TINF2 gene, eight of which are novel." (PMID 21199492, 2012). "The incidence of aplastic anaemia is greater in patients with TERC or TINF2 mutations compared to patients with DKC1 mutations, and cancer incidence is highest in patients with TERC mutations." (PMID 21931702, 2011). "Conversely, most patients with TINF2 mutations develop TBDs other than the classical phenotype of RS, including not only 11 to 24% of DKC patients, but also HHS, idiopathic pulmonary fibrosis, and aplastic anemia." (PMID 33097095, 2020).
bone marrow failure syndrome (5 papers, 2011 to 2024). "While the loss-of-function mutations described here cause cancer through aberrant telomere elongation, missense mutations in the DC patch of TINF2 cause bone-marrow failure syndromes that are due to excessive telomere shortening." (PMID 33258446, 2020). "Recently, germ-line mutations in TINF2, which encodes for the TIN2 protein, have been identified in a number of patients with bone-marrow failure syndromes." (PMID 21731707, 2011).
breast carcinoma (5 papers, 2012 to 2023). "Based on the case-control comparisons, the frequency of TINF2 p.Tyr312Ter in breast cancer cases was 4-fold higher compared to controls, which falls at most into the range typical for moderate breast cancer risk alleles." (PMID 35590014, 2023). "Recent reports indicate that specific TINF2 truncating mutations act as high penetrance cancer predisposition alleles outside DC context, including breast cancer in their tumor spectrum." (PMID 35590014, 2023). "Although TINF2 p.Tyr312Ter variant was recurrent in breast cancer cases, it is also reported in public databases in apparently healthy individuals." (PMID 35590014, 2023). "Here, we have evaluated the role of TINF2 and other shelterin complex gene mutations in inherited breast cancer susceptibility." (PMID 35590014, 2023). "As a result, we report a recurrent TINF2 truncation mutation, p.Tyr312Ter, which based on case-control comparisons is at highest a moderate-risk allele for breast cancer." (PMID 35590014, 2023). "A single protein truncating variant, TINF2 p.Tyr312Ter, was identified in one of the cases (1/98), and four more carriers were observed in the subsequently genotyped unselected breast cancer cohort (4/1904)." (PMID 35590014, 2023). "Our results provide additional evidence that TINF2 mutations in different gene positions can have remarkably diverse effects on individuals’ phenotype, ranging from severe congenital disorder to potentially moderately increased risk for breast cancer." (PMID 35590014, 2023). "To evaluate the role of germline mutations in TINF2 and other shelterin encoding genes in inherited breast cancer susceptibility, we analyzed exome sequencing data from 98 Northern Finnish breast cancer cases with indication of hereditary disease susceptibility." (PMID 35590014, 2023). "Here, we have evaluated the role of germline mutations in TINF2 and other shelterin genes in inherited breast cancer susceptibility using exome sequencing data from 98 Northern Finnish breast cancer cases with indication of inherited disease predisposition as a discovery cohort." (PMID 35590014, 2023). "Although recurrent in cases (total of 5/2095), TINF2 p.Tyr312Ter is also present in Finnish population controls (8/12,517), and the observed 4-fold higher frequency in cases falls at most into the range of moderate breast cancer risk alleles (OR 3.74, 95% CI 1.22–11.45, p = 0.029)." (PMID 35590014, 2023).
pulmonary fibrosis (5 papers, 2016 to 2025). Chronic progressive interstitial lung disorder characterized by the replacement of the lung tissue by connective tissue, leading to progressive dyspnea, respiratory failure, or right heart failure. "This is the first report of a TINF2 mutation in a patient with sporadic pulmonary fibrosis, which represents another association between TINF2 mutations and this disease." (PMID 27088026, 2016). "Previously, TINF2 mutations were found in three DC patients that developed pulmonary fibrosis and in a family with pulmonary fibrosis, infertility, and short telomeres." (PMID 27088026, 2016). "The association between the Ser245Tyr TINF2 gene mutation, pulmonary fibrosis, and hypogammaglobulinemia needs to be validated in other cohorts." (PMID 27088026, 2016). "When combining this with the (probably) damaging nature of the Ser245Tyr TINF2 gene mutation, we find it the most plausible that our patients' pulmonary fibrosis was an independent manifestation of a telomere syndrome." (PMID 27088026, 2016). "In summary, we identified a heterozygous Ser245Tyr mutation in the TINF2 gene of a sporadic pulmonary fibrosis patient." (PMID 27088026, 2016). "Given that pulmonary interstitial fibrosis is independently attributed to TINF2-mutations, lung disease due to insufficient telomere maintenance may be regarded as an obligatory late sequela in patients with RS also without SCT." (PMID 33097095, 2020). "A TINF2 gene mutation was recently reported in a family with pulmonary fibrosis." (PMID 27088026, 2016). "This case represents another association between TINF2 mutations and pulmonary fibrosis." (PMID 27088026, 2016). "First, this case represents another association between TINF2 mutations and pulmonary fibrosis." (PMID 27088026, 2016). "Therefore, we performed a sequence analysis of TINF2 in our cohort of 158 pulmonary fibrosis patients, which revealed a heterozygous Ser245Tyr mutation in one patient." (PMID 27088026, 2016).
Revesz syndrome (5 papers, 2018 to 2025). "DKCA5 (Revesz syndrome) is caused by mutations in the TINF2 gene, which is also the mutated gene of DKCA3." (PMID 37372478, 2023). "Mutations in TINF2 are linked to Revesz syndrome, a telomeropathy with symptoms characteristic of accelerated aging." (PMID 31921313, 2019).
bone marrow failure (4 papers, 2012 to 2023). "Over the same period, we have also been looking for TINF2 mutations among patients who have bone marrow failure but do not have the clinical hallmarks of DC: this series comprised 122 patients with AA and 57 patients in whom there are some features that overlap DC." (PMID 21199492, 2012). "We recently described the VUS Ser245Tyr on the TINF2 gene in other patients with bone marrow failure in whom, unfortunately, we could not perform the telomere length analysis." (PMID 36498862, 2022).
lymphoma (3 papers, 2017 to 2024). A malignant (clonal) proliferation of B- lymphocytes or T- lymphocytes which involves the lymph nodes, bone marrow and/or extranodal sites. "The risk of solid tumors was highest in individuals with AR/XLR (O:E, 23.97 [95% CI, 10.96-45.50]), whereas O:Es for hematologic malignant neoplasms (including lymphoma) was higher in individuals with AD–non-TINF2 (O:E, 9.41 [95% CI, 4.3-17.86]." (PMID 39661387, 2024).
telomere syndrome (3 papers, 2016 to 2019). Accelerated aging syndromes often caused by inheritable gene mutations resulting in decreased telomere lengths. "TIN2 is an important regulator of telomere length, and mutations in TINF2, the gene encoding TIN2, cause short-telomere syndromes." (PMID 31383750, 2019). "TIN2, encoded by the TINF2 gene, is essential for shelterin assembly at the telomere and is mutated in patients with severe short-telomere syndromes." (PMID 31383750, 2019). "However, the mutation has been associated with a telomere syndrome phenotype in three patients (four when our patient is included), and therefore others consider the Ser245Tyr mutation to be pathogenic, but associated with a milder telomere syndrome phenotype compared to other TINF2 mutations." (PMID 27088026, 2016). "The majority of the TINF2 mutations found in telomere syndrome patients lie in a cluster outside the binding regions of TINF2 to shelterin proteins TRF1, TRF2, and TPP1 and do not seem to influence the interaction of TINF2 with these proteins." (PMID 27088026, 2016).
exudative retinopathy (2 papers, 2020 to 2022). "Conversely, patients with features of RS including early onset of BMF and TINF2-mutations but lacking exudative retinopathy are published in the literature." (PMID 33097095, 2020).
acute myeloid leukemia (1 paper, 2024). Acute myeloid leukemia (AML) is a group of neoplasms arising from precursor cells committed to the myeloid cell-line differentiation. "TERF1, TERF2, TINF2, and POT1 are significantly expressed in testicular, Acute Myeloid Leukemia (AML), prostate and breast as well as renal cancers, respectively." (PMID 39578854, 2024).
autism (1 paper, 2025). Persistent deficits in social interaction and communication and interaction as well as a markedly restricted repertoire of activity and interest as well as repetitive patterns of behavior. "In VPA females’ model of autism, nooclerin exerted the most pronounced influence on alterations in the transcriptional activities of the tnks genes, telomerase (Tep1, Dkc1) and the shelterin complex (Terf2ip, Pot1a, Tinf2, Tpp1, Trf1 - 2) in the hippocampus." (PMID 40272729, 2025).
GI hemorrhage (1 paper, 2022). "It is interesting that the phenotype of patients with DC/TBD due to PVs in TINF2 has important vascular features such as PAVMs, GI hemorrhage, and in the exudative retinopathy found in RS." (PMID 36091172, 2022). "PVs in the gene TINF2 were more frequently detected in patients who had GI hemorrhage." (PMID 36091172, 2022).
Hydrocephalus (1 paper, 2021). Hydrocephalus is an active distension of the ventricular system of the brain resulting from inadequate passage of CSF from its point of production within the cerebral ventricles to its point of absorption into the systemic circulation. "Although the sample size in this study was relatively small, we consider that DKC instances in South China may be more likely to be related to TINF2 mutations and female DKC patients may be more prone to hydrocephalus." (PMID 33734615, 2021).
leukemia (1 paper, 2011). A malignant (clonal) hematologic disorder, involving hematopoietic stem cells and characterized by the presence of primitive or atypical myeloid or lymphoid cells in the bone marrow and the blood. "As such, we validated the functionality of the core TINF2 promoter by transfecting the P450 construct into various cancer cell lines, including human leukemia K562 cells and Jurkat cells." (PMID 21731707, 2011).
liver disorder (1 paper, 2022). A disease involving the liver. "In a cohort of 121 individuals with telomeropathies and variants in TERT, TERC, and TINF2, 40% were found to have some extent of liver disorder." (PMID 36311538, 2022).
Nail dystrophy (1 paper, 2022). Onychodystrophy (nail dystrophy) refers to nail changes apart from changes of the color (nail dyschromia) and involves partial or complete disruption of the various keratinous layers of the nail plate. "The TINF2 mutation was phenotypically associated with short stature in the proband, nail dystrophy and spotted hypopigmentation in her mother, and psoriasis in her older brother." (PMID 35873475, 2022).